MTND1P5 (MT-ND1 pseudogene 5)
Gene: Processed pseudogene on chromosome 8 (103,085,651 to 103,086,590, forward strand). Ensembl gene ENSG00000253795.
Diseases named in the same sentence as MTND1P5 in open-access papers:
MTND1P5 is named in the same sentence as 1 disease in open-access papers, as found by Europe PMC text mining. Sharing a sentence is not in itself a finding about the gene and the disease. The quoted sentences say what the papers report.
periodontitis (1 paper, 2019). An acute or chronic inflammatory process that affects the tissues that surround and support the teeth. "We, therefore, used four SNPs, in LOC107984137, MTND1P5, DEFA1A3, and SIGLEC5 loci, previously associated with periodontitis in GWAS, as instruments for making causal inferences about the role of periodontitis in human BP regulation." (PMID 31504461, 2019).